CAMKMT (calmodulin-lysine N-methyltransferase)
Description:
Catalyzes the trimethylation of 'Lys-116' in calmodulin.
Synonyms: CLNMT; CaM KMT; C2orf34; Cam; KMT
Tractability: Small molecule: a structure with a bound ligand is known. PROTAC: ubiquitination databases record sites on it; its protein half-life has been measured.
Gene: Protein-coding gene on chromosome 2 (44,361,947 to 44,772,592, forward strand). Ensembl gene ENSG00000143919.
Subcellular location: Cytoplasm (Isoform 1); Nucleus; Golgi apparatus (Isoform 2)
Subcellular location (Human Protein Atlas): Nucleoplasm; Nucleoli
Pathways (Reactome):
Metabolism of proteins: Protein methylation
Sensory Perception: Inactivation, recovery and regulation of the phototransduction cascade
Gene Ontology:
Molecular function: heat shock protein binding; calmodulin-lysine N-methyltransferase activity
Biological process: regulation of opsin-mediated signaling pathway
Cellular component: cytoplasm; Golgi apparatus; nucleolus; nucleoplasm; nucleus; protein-containing complex; cytosol
Genetic constraint (gnomAD): Loss-of-function variants: 28 observed, 23.28 expected, observed/expected ratio (o/e) 1.2, 90% interval 0.89 to 1.64. The synonymous counts are far from expectation, so gnomAD's model fits this gene poorly and the ratio says little. Missense variants: 296 observed, 251.78 expected, observed/expected ratio (o/e) 1.18, 90% interval 1.07 to 1.29. Synonymous variants: 130 observed, 98.94 expected, observed/expected ratio (o/e) 1.31, 90% interval 1.14 to 1.52.
Homologues: Orthologues: chimpanzee CAMKMT (99% identical), macaque CAMKMT (98% identical), dog CAMKMT (90% identical), rabbit CAMKMT (89% identical), pig CAMKMT (87% identical), guinea pig CAMKMT (86% identical), rat Camkmt (84% identical), mouse Camkmt (84% identical), tropical clawed frog camkmt (67% identical), zebrafish camkmt (55% identical), Drosophila melanogaster CG10947 (36% identical), zebrafish camkmt (19% identical).
Diseases named in the same sentence as CAMKMT in open-access papers:
CAMKMT is named in the same sentence as 19 diseases in open-access papers, as found by Europe PMC text mining. Sharing a sentence is not in itself a finding about the gene and the disease. The quoted sentences say what the papers report.
cystinuria (4 papers, 2012 to 2022). Cystinuria is a renal tubular amino acid transport disorder characterized by recurrent formation of kidneys cystine stones. "In humans a deletion of the 2p21 region including four genes (PP2Cβ, SLC3A1, PREPL and CAMKMT) was described as a syndrome (MIM #606,407) associated with cystinuria, intellectual disability, mitochondrial disease, hypotonia and facial dysmorphism." (PMID 31865460, 2020).
Intellectual disability (3 papers, 2018 to 2023). "Deletion of a genomic region including CAMKMT in humans has been associated with micrognathia, dolichocephaly, and cleft palate, although the specific loss of CAMKMT has been associated with intellectual disability and muscle fiber abnormalities instead of these craniofacial phenotypes." (PMID 29423138, 2018). "CAMKMT is linked to Hypotonia-Cystinuria Syndrome (OMIM #606407), which manifests as mild to moderate intellectual disability and respiratory chain complex IV deficiency." (PMID 37664546, 2023).
Anxiety (2 papers, 2020 to 2022). Intense feelings of nervousness, tension, or panic often arise in response to interpersonal stresses. "CAMKMT catalyzes Lys-116 trimethylation in calmodulin, and other CAMKMT polymorphisms have been associated with anxiety risk." (PMID 35512135, 2022).
anxiety disorder (2 papers, 2021 to 2024). A category of psychiatric disorders which are characterized by anxious feelings or fear often accompanied by physical symptoms associated with anxiety. "For anxiety disorders, 18 SNPs are linked to genes including CAMKMT, ARPP19, SOCS5, TNS3, VWDE, TSHZ2, and others." (PMID 39165506, 2024). "Specifically, CAMKMT influences anxiety disorders through CAMKII methylation, which impacts neuronal function and synaptic plasticity, showing significant genetic associations in European populations." (PMID 39165506, 2024). "Notably, entities such as CAMKMT, NCKAP5, CASC8, and rs56242606 exhibit positive associations with anxiety disorders." (PMID 39165506, 2024). "A meta-analysis of nine anxiety disorder GWAS identified an uncharacterized non-coding RNA locus (LOC152225) associated with lifetime diagnosis of anxiety spectrum disorders, and the gene Calmodulin-Lysine N-Methyltransferase (CAMKMT) associated with latent anxiety disorder factor-score model." (PMID 33431988, 2021).
cancer (3 papers, 2016 to 2025). A tumor composed of atypical neoplastic, often pleomorphic cells that invade other tissues. "In addition, qPCR confirmed that many NDD-related genes, such as CAMKMT, COX15, and GAS7 involved in neurodevelopment and cancer, were downregulated in the patients." (PMID 37664546, 2023).
mitochondrial disease (2 papers, 2020 to 2021). "In contrast, the presence of mitochondrial disease is relatively common in “2p21 microdeletion syndrome” which involves the deletion of at least four contiguous genes on chromosome 2, SLC3A1, PREPL, PPM1B, and CAMKMT." (PMID 34612606, 2021).
tumor (1 paper, 2024). "In contrast, CAMKMT and METTL18 both promoted tumor activity, but through different mechanisms: CAMKMT directly interacted with and likely methylated Src (detailed Src activation mechanisms by CAMKMT are currently being explored, data not shown), while METTL18 did not directly bind to Src." (PMID 39309445, 2024).
CAMKMT also shares sentences with these, for which no sentence is quoted: developmental delay (2 papers); hypotonia-cystinuria syndrome (2); Parkinson disease (2); autism spectrum disorder (1); brain-disease (1); cleft palate (1); Hypotonia (1); infection (1); Kabuki syndrome (1); Micrognathia (1); neurodevelopmental disorder (1); soft tissue sarcoma (1).